NLRX1 (NLR family member X1)
Diseases named in the same sentence as NLRX1 in open-access papers (continued):
Sharing a sentence is not in itself a finding about the gene and the disease.
tumor (19 papers, 2014 to 2026). "Conversely, the loss of NLRX1 in Pan02 cells contributes to mitochondrial dysfunction that is consistent with tumor-associated characteristics." (PMID 37342194, 2023). "NLRX1 deficiency in the tumour cells promoted CD8+ CTL expansion located in the tumour‐draining lymph nodes and reduces CTL exhaustion in the TME." (PMID 33605033, 2021). "Here, we showed that NLRX1 serves as a tumor suppressor in HCC, and its expression is associated with improved prognosis." (PMID 29482578, 2018). "High NOD2 and low NLRX1 expression in tumor tissue was associated with short MST (P = 0.012 and 0.014, respectively)." (PMID 28960882, 2017). "In contrast, tumor challenge caused a significant increase in the expression of NLRX1." (PMID 27198666, 2016). "Together, these data suggest that NLRX1 expressed by Pan02 cells is tumor suppressive through limiting proliferation, mitochondrial ROS levels, and migration, while also increasing cell death." (PMID 37342194, 2023). "Together, these data indicate a tumor suppressive role for NLRX1 in Pan02 cells where it protects against unregulated mitochondrial activity and limits the energy available to the cell." (PMID 37342194, 2023). "Specifically, the protective roles of NLRX1 in various tumor models seem to converge on NF-κB and AKT signaling." (PMID 37342194, 2023). "As a proxy for potential metastatic ability, we next measured how NLRX1 impacts migratory capacity using a wound healing assay and calculating the rate of migration of the tumor cells." (PMID 37342194, 2023). "This suggests the loss of NLRX1 in Pan02 cells promotes the migratory capabilities of the tumor cell and would indicate a potential for increased metastasis when NLRX1 expression in the tumor is decreased." (PMID 37342194, 2023). "The gene expression signatures here suggest a strong role for NLRX1 in limiting inflammation, including through NF-κB signaling and inflammasomes, inducing an anti-tumor immune microenvironment, and protecting against damaging cellular stress signals." (PMID 37342194, 2023). "Contrary to previous data, which characterized NLRX1 as a tumor suppressor by inhibiting tumor promoting signaling pathways such as Akt, NF-κB or MAPK, it was also reported that NLRX1 contributes to tumorigenesis by regulating cell death." (PMID 33525671, 2021). "Since the role of NLRX1 in the regulation of tumor cell functions has been extensively reviewed elsewhere, we do not detail further in this paper." (PMID 33525671, 2021). "An intrinsic tumor suppressor, an NLRX1 gene product, was shown in intestinal epithelial cells acting as an inhibitor of key tumor-promoting pathways." (PMID 30976817, 2019). "Low tumor NLRX1 expression was identified as an independent indicator for HCC prognosis (recurrence: hazard ratio [HR] 1.87, 95% confidence interval [CI] 1.26–2.76, overall survival [OS] 2.26, 95% CI 1.44–3.56)." (PMID 29482578, 2018). "First, we investigated the expression patterns of NLRX1 between HCC tumor tissues and paired adjacent normal liver tissues." (PMID 29482578, 2018). "NLRX1 acted as a tumor suppressor in HCC by inducing apoptosis, promoting senescence, and decreasing invasiveness by repressing PI3K-AKT signaling pathway." (PMID 29482578, 2018). "A recent pair of studies have suggested that NLRX1 functions as a tumor suppressor through modulating apoptosis." (PMID 27105514, 2016). "The results obtained in the present study support previous findings and strongly suggest that NLRX1 functions to attenuate tumor progression." (PMID 27105514, 2016). "In the presence of TNF, NLRX1 knockdown resulted in significantly increased tumor volume, whereas overexpression attenuated tumor growth." (PMID 27105514, 2016). "In the other study, NLRX1 was found to function as a tumor suppressor by regulating TNF induced apoptosis in immortalized cell lines." (PMID 27105514, 2016). "This suggests a possible link between reduced NLRX1 levels and increased NF-λB signaling in this neoplasm." (PMID 27105514, 2016).
tumor (continued). "Detailed analysis of proliferation versus apoptosis in WT and NLRX1−/− intestinal crypts at different stages of tumor development will be critical to provide mechanistic insights into the differential role played by this molecule in AOM and AOM/DSS CRC models." (PMID 24867956, 2014). "In one study, knockdown of NLRX1 in HeLa cells reversed the acidification of the culture medium, suggesting that NLRX1 may contribute to the metabolic switch to glycolysis in tumor cells." (PMID 34697412, 2022). "Collectively, these results indicate that NLRX1 might act as a tumor suppressor and be a useful prognostic biomarker in HCC." (PMID 29482578, 2018). "The effect of NLRX1 on tumor cell apoptosis was also investigated using flow cytometry." (PMID 29482578, 2018). "In summary, our present work identified NLRX1 as a tumor suppressor in HCC." (PMID 29482578, 2018). "Moreover, our results demonstrate that NLRX1 impairs tumor invasiveness by inhibiting EMT—a critical biological process for HCC progression—and promotes cell senescence in a P21-dependent manner." (PMID 29482578, 2018). "The present findings support previous studies reporting that NLRX1 attenuates tumor progression." (PMID 29482578, 2018). "To investigate the effect of NLRX1 on tumor growth, we first conducted CCK-8 assays." (PMID 29482578, 2018). "Recent publications have suggested a role for the NLR, NLRX1, in acting as a tumor suppressor." (PMID 27105514, 2016). "Besides regulating host-pathogen interactions, NLRX1 acts as a tumor suppressor or, on the contrary, might facilitate metastasis development." (PMID 33525671, 2021). "In addition to negatively regulating NF-κB signaling, NLRX1 also serves as a tumor suppressor." (PMID 33525671, 2021). "Moreover, tumor growth was greatly impaired by NLRX1 OE during in vivo experiments." (PMID 29482578, 2018). "However, these approaches would have to take into consideration the fact that NLRX1 inhibition might also increase the resistance of tumor cells to intrinsic signals, such as nutrient withdrawal." (PMID 24867956, 2014). "In vivo, NLRX1-mediated inhibition of anti-tumor immunity was IFN-I-dependent, which was evidenced by the comparable levels of tumor volumes and STING signature genes between groups in Ifnar1–/– hosts." (PMID 41142804, 2025). "The knockout of NLRX1 could significantly decrease IFN-I dependent T cell infiltration and inhibit tumor progression." (PMID 34108990, 2021). "Furthermore, NLRX1 impaired the activity of mitochondrial ETC components and supported aerobic glycolysis in tumour cells." (PMID 33525671, 2021). "Scatter plots of NOD1, NOD2, and NLRX1 mRNA expression level in the GEO database revealed that only NOD1 expression differed significantly between tumor and nontumor tissue (P = 0.007)." (PMID 28960882, 2017). "Interestingly, they found that NLRX1 mediates cell death in neoplastic but not in normal cells and suggest that NLRX1 mediates tumor suppression through the induction of apoptosis." (PMID 33525671, 2021). "NLRX1 was downregulated in tumor tissue compared with adjacent normal liver tissue." (PMID 29482578, 2018). "We speculate that NLRX1 expression will reflect the relative exposure to intrinsic apoptosis signals (such as nutrient availability) versus extrinsic apoptosis signals (such as inflammation-derived factors, including TNF) in normal tissue or the tumor microenvironment." (PMID 24867956, 2014).
bacterial infections (6 papers, 2011 to 2022). "Several studies have reported a downregulation of NLRX1 in different experimental models such as viral and bacterial infections and brain injury." (PMID 35651602, 2022). "NLR Family Member X1 (NLRX1) was shown to inhibit the association between RIG-I and MAVS and TRAF6-dependent IKK activation in response to viral or bacterial infection." (PMID 33808506, 2021). "Originally identified to utilize the mitochondrion as a platform to mediate antiviral responses, NLRX1 now appears to also be important for immune responses to bacterial infections as well." (PMID 21339989, 2011). "NLRX1-induced ROS appears to be critical for bacterial infections, especially in terms of its signaling properties." (PMID 21339989, 2011). "Leptotrichia showed a negative association with NLRX1, which plays a role in host immunity during bacterial infections." (PMID 33809523, 2021). "NLRX1 gene plays a pivotal in host immunity when it comes to bacterial infections." (PMID 34201826, 2021).
neurodegenerative disease (4 papers, 2014 to 2025). A disorder of the central nervous system characterized by gradual and progressive loss of neural tissue and neurologic function. "Consequently, NLRX1 represents a potential therapeutic target for the inflammatory and neurodegenerative diseases associated with glutamate excitotoxicity in the CNS." (PMID 31052241, 2019). "This study highlights that NLRX1 could serve as a promising target for neuroprotection in progressive MS and other neurodegenerative diseases." (PMID 39875919, 2025). "Nlrx1 may play an important role in neurodegenerative diseases, where necrosis is a prominent factor." (PMID 25540124, 2014).
central nervous system diseases (1 paper, 2024). "Nucleotide-binding oligomerization domain, leucine-rich repeat-containing X1 (NLRX1) functions as a scaffolding protein and is involved in various central nervous system diseases." (PMID 38671928, 2024).
gastrointestinal disorders (1 paper, 2022). "Studies have yet to evaluate the gut microbiome following NLRX1-deficiency and CeD pathogenesis; however, this negative regulatory NLR, NLRX1, has been evaluated in other gastrointestinal disorders." (PMID 35572547, 2022).
NLRX1 also shares sentences with these, for which no sentence is quoted: head and neck cancer (2 papers); osteoarthritis (2); Parkinson's (2); cerebral infarction (1); cervical carcinoma (1); Crohn disease (1); diabetic nephropathy (1); disc degeneration (1); fibrosis (1); hypertrophy (1); lupus (1); malignant fibrous histiocytoma (1); Metastatic cancer (1); neurological diseases (1); Obesity (1); Polydipsia (1); primary sclerosing cholangitis (1); type 2 diabetes mellitus (1).